SI (sucrase-isomaltase)
Description:
Bifunctional enzyme with both sucrase and isomaltase activities involved in breakdown of dietary starch oligosaccharides in small intestine. The isomaltase domain hydrolazes alpha-1,6-glycosidic linkages in isomaltose. The sucrase domain cleaves the alpha-1,2-glycosidic linkages in sucrose to form glucose and fructose, and contributes to the cleavage of the alpha-1,4-glycosidic linkage in maltose to form two glucose monosaccharides.
Tractability: Small molecule: an approved drug acts on it; a structure with a bound ligand is known; a high-quality ligand is known; it has a high-quality binding pocket; it belongs to a druggable protein family. Antibody: its Gene Ontology location is reachable by antibodies, with high confidence; UniProt places it where antibodies can reach, with medium confidence; UniProt predicts a signal peptide or a membrane-spanning region. PROTAC: a small molecule that binds it is known.
Target class: Enzyme; Hydrolase
Gene: Protein-coding gene on chromosome 3 (164,978,898 to 165,078,496, reverse strand). Ensembl gene ENSG00000090402.
Subcellular location: Apical cell membrane
Pathways (Reactome):
Digestion and absorption: Digestion of dietary carbohydrate
Disease: Intestinal saccharidase deficiencies
Gene Ontology:
Molecular function: alpha-1,4-glucosidase activity; oligo-1,6-glucosidase activity; protein binding; sucrose alpha-glucosidase activity; alpha-glucosidase activity; carbohydrate binding; hydrolase activity, hydrolyzing O-glycosyl compounds
Biological process: sucrose catabolic process; polysaccharide digestion; carbohydrate metabolic process; disaccharide catabolic process
Cellular component: extracellular exosome; brush border; brush border membrane; Golgi apparatus; plasma membrane; apical part of cell; apical plasma membrane
Genetic constraint (gnomAD): Loss-of-function variants: 109 observed, 126.67 expected, observed/expected ratio (o/e) 0.86, 90% interval 0.74 to 1.01. The upper end of that interval is the gene's LOEUF score, 1.01, which puts it in group 4 of 6, group 1 being the genes least tolerant of losing a copy. Missense variants: 1,366 observed, 1,278.1 expected, observed/expected ratio (o/e) 1.07, 90% interval 1.02 to 1.12. Synonymous variants: 448 observed, 420.52 expected, observed/expected ratio (o/e) 1.07, 90% interval 0.99 to 1.15.
Homologues: Orthologues: chimpanzee SI (99% identical), macaque SI (95% identical), pig SI (84% identical), dog SI (84% identical), rabbit SI (82% identical), guinea pig SI (81% identical), rat Si (78% identical), mouse Sis (78% identical), Caenorhabditis elegans aagr-2 (20% identical), Caenorhabditis elegans aagr-4 (13% identical), Drosophila melanogaster GCS2alpha (12% identical), zebrafish si:ch211-236l14.4 (6% identical), and 1 more. Paralogues in human: MGAM (59% identical), MGAM2 (56% identical), GAA (21% identical), GANAB (14% identical), GANC (13% identical), MYORG (7% identical).
Diseases named in the same sentence as SI in open-access papers:
SI is named in the same sentence as 40 diseases in open-access papers, as found by Europe PMC text mining. Sharing a sentence is not in itself a finding about the gene and the disease. The quoted sentences say what the papers report.
congenital sucrase-isomaltase deficiency (11 papers, 2016 to 2025). A disorder of carbohydrate absorption and transport caused by autosomal recessive mutation of the SI gene, characterized by malabsorption of sucrose and maltose. "Congenital sucrase-isomaltase deficiency (CSID) is a genetically determined primary defect of sucrase-isomaltase (SI) that is associated with carbohydrate malabsorption." (PMID 33920345, 2021). "Saccharose intolerance arises from deficiencies in sucrase-isomaltase enzyme function, caused by congenital sucrase-isomaltase deficiency (CSID) or secondary factors such as celiac disease or Crohn’s disease." (PMID 40284223, 2025). "Congenital sucrase-isomaltase deficiency (CSID) is a rare autosomal recessive condition with mutations of the sucrase-isomaltase gene on chromosome 3q25-26." (PMID 35565890, 2022). "Mutations interfering with O-linked glycosylation of the sucrase-isomaltase (SI) enzyme are believed to be associated with aberrant sorting of SI to the basolateral membrane in congenital sucrase-isomaltase deficiency (CSID)." (PMID 29590640, 2018). "Congenital sucrase isomaltase deficiency (CSID), also known as genetic sucrase deficiency, is a multifaceted intestinal malabsorption disorder with an autosomal recessive mutation in the sucrase-isomaltase (SI) gene on chromosome 3 (3q25-q26)." (PMID 33972906, 2021). "Congenital sucrase-isomaltase deficiency (CSID) is an autosomal recessive disorder of carbohydrate maldigestion and malabsorption caused by mutations in the sucrase-isomaltase (SI) gene." (PMID 31557950, 2019). "Congenital sucrase-isomaltase deficiency (CSID), now called genetic SI deficiency, is the inability to digest sucrose and starch due to mutations in the SI gene that lead to no function." (PMID 41008568, 2025). "Congenital sucrase-isomaltase deficiency (CSID) is a rare metabolic intestinal disorder with reduced or absent activity levels of sucrase-isomaltase (SI)." (PMID 33375084, 2020).
colon cancer (3 papers, 2012 to 2017). "Our data regarding the importance of C-terminus in Cdx2-dependent transcriptional regulation is well supported by a previous study where deletion of the Cdx2 C-terminus (Cdx2CD) also reduced sucrase isomaltase reporter activity by ∼50% in colon cancer cells." (PMID 22719836, 2012). "Furthermore, we also observed that LTC4, via the CysLT2/JNK signaling pathway, increased the expression of the differentiation markers sucrase-isomaltase and mucin-2 in colon cancer cells and that down-regulation of 15-PGDH totally abolished the observed increase in these markers." (PMID 28402256, 2017).
colitis (2 papers, 2021 to 2024). Inflammation of the colon. "Restoration of protein trafficking with RCME was reported in a previous study, in a Caco-2 cell model of DSS-induced colitis, in which the impaired trafficking and polarized sorting of sucrase-isomaltase and dipeptidyl-peptidase were restored with RCME treatment." (PMID 39518914, 2024). "In IBD patients, DSS-induced colitis animal models, as well as DSS-treated Caco-2 cells, the cell surface expression and activity of various intestinal hydrolases such as SI and DPP4 is altered." (PMID 33572926, 2021).
deficiencies (2 papers, 2016 to 2021). "Previous studies have reported some associations between congenital sucrase-isomaltase deficiencies and IBS but no clear association of lactase deficiency with IBS14–16." (PMID 33649365, 2021).
irritable bowel syndrome (2 papers, 2019 to 2020). Irritable bowel syndrome (IBS) is a chronic functional condition of the lower gastrointestinal (GI) tract characterized by abdominal pain or discomfort and disordered bowel habit (diarrhea, constipation, or fluctuation between the two). "More recently, several new mutations in the SI gene have been tested by genotyping in a panel of patients suffering from irritable bowel syndrome (IBS) symptoms." (PMID 31557950, 2019).
cardiomyopathy (1 paper, 2024). A disease of the heart muscle or myocardium proper. "These five pathogenetic HDV loci are associated with the susceptibility of osteopetrosis (CLCN7), hearing loss (GJB2), cardiomyopathy (PRDM16), arrhythmogenic right ventricular dysplasia 1 (TGFB3), and sucrase-isomaltase deficiency (SI), respectively." (PMID 38448908, 2024).
celiac disease (1 paper, 2019). An autoimmune genetic disorder with an unknown pattern of inheritance that primarily affects the digestive tract. "Using quantitative PCR (qPCR) confirmed the reduction in sucrase-isomaltase (SI) and APOA1 genes expression levels in celiac disease." (PMID 31700112, 2019).
Obesity (1 paper, 2016). Accumulation of substantial excess body fat. "Among these candidates, butyrylcholinesterase (Bche) and Sucrase-isomaltase (Si) peptidylprolyl isomerase D (PpiD) and electron-transferring-flavoprotein dehydrogenase (EtfdH) are all well-known for body weight or obesity." (PMID 27203862, 2016).
spermatogenic failure (1 paper, 2023). A male infertility characterized by dirsuption of the process of sperm development from diploid cells into mature haploid spermatozoa. "Our study found that the expression of SI (sucrase-isomaltase) and DHX57 (DExH-box helicase 57) was reported in healthy testis, but the expression of both genes decreased significantly in NOA patients, which might indicate abnormalities in glycometabolism and RNA metabolism in spermatogenic failure." (PMID 36945018, 2023).
type 2 diabetes (1 paper, 2023). "A theoretical analysis of the potential inhibition of human sucrase-isomaltase (SI) by flavonoids was carried out with the aim of identifying potential candidates for an alternative treatment of type 2 diabetes." (PMID 37836621, 2023).
cancer (8 papers, 2015 to 2024). A tumor composed of atypical neoplastic, often pleomorphic cells that invade other tissues. "Sucrase-isomaltase (SI) is a carbohydrate metabolism enzyme and SI gene mutations involve in the metabolism and development of cancer." (PMID 35761419, 2022). "For the three cancers, SNVs were more likely to be detected in the high-OGT expression group than in the low-OTG expression group, and the top five genes with the highest frequency of SNV were MUC17, PIK3CA, SI, SYNE1, and PTEN." (PMID 35356257, 2022). "However, sucrase-isomaltase (SI), an intestinal mucosa α-glucosidase was previously detected in human bile but not related to cancer." (PMID 32575903, 2020).
tumor (5 papers, 2015 to 2024). "The expression of the differentiation marker, sucrase isomaltase (SI) and the pro-apoptotic marker, Bcl-2 associated X protein (BAX) were significantly down-regulated in the tumor samples compared with the adjacent mucosa (n = 54, p < 0.001)." (PMID 25701758, 2015). "Among the 17 overexpressed genes, CDX1 (caudal type homeobox 1) had the highest fold difference in tumor versus non-tumor tissues followed by SI (sucrase-isomaltase, aka alpha-glucosidase), KRT16 (keratin 16) and SERPINB5 (serpin peptidase inhibitor, clade B (ovalbumin), member 5)." (PMID 28418924, 2017). "In addition, we measured the expression of a number of other genes in the tumours including nuclear receptors (VDR, RXRα, SXR, ER α and β), cytochrome P450 enzyme (CYP3A4), proliferation marker (MCM2, CDC6, KI67), differentiation marker (sucrase isomaltase) and angiogenesis marker (CD31)." (PMID 26238339, 2016). "Among the 17 upregulated genes, we selected the top five, i.e. CDX1, SI, KRT16, HOXA10, and SERPINB5 for validation using RT-PCR in the 20 pairs of tumor and non-tumor tissues that were not used in RNA-seq." (PMID 28418924, 2017).
genetic disorder (2 papers, 2014 to 2021). "Congenital sucrase-isomaltase deficiency (CSID) is a rare genetic disorder characterized by a deficiency of the sucrase-isomaltase (SI) enzyme complex within the brush border membrane of the small intestine." (PMID 33772704, 2021). "Initially described by Weijers and colleagues in 1960, CSID is generally considered a rare hereditary disease caused by mutations of the sucrase-isomaltase gene." (PMID 24433566, 2014).
cardiovascular disease (1 paper, 2021). "Overall, 86 genes were identified to significantly modify the cardiovascular disease severity in PXE, of which four genes are present in both tests (HCAR3, CNGB3, SI, and PRKAR1A)." (PMID 34169069, 2021).
SI also shares sentences with these, for which no sentence is quoted: infection (3 papers); adenoma (2); acute intermittent porphyria (1); angiosarcoma (1); breast carcinoma (1); Burkitt lymphoma (1); Congenital erythropoietic porphyria (1); Crohn disease (1); cystic fibrosis (1); dental caries (1); diabetes (1); diarrhoea (1); gangliosidosis (1); hearing loss (1); hereditary coproporphyria (1); Hyperglycemia (1); Infantile Sialic Acid Storage Disease (1); lung adenocarcinoma (1); lymphoma (1); mucinous adenocarcinoma (1); osteopetrosis (1); Porphyria variegata (1); Rotavirus infection (1); Salla disease (1); sialuria (1); Tay-Sachs disease (1).